BRCA2 (BRCA2 DNA repair associated)
Diseases named in the same sentence as BRCA2 in open-access papers (continued):
Sharing a sentence is not in itself a finding about the gene and the disease.
tumor (continued). "Thus, with the identification of both a BRCA2 mutation and ERCC1 negativity, this case clearly demonstrates the benefit of molecular profiling in optimising therapy for this rare tumour and avoiding aggressive protocols from which the patient was unlikely to derive benefit." (PMID 27488020, 2016). "Therefore, BRCA2 ASO treatment has the potential to render a high proportion of tumor cells sensitive to olaparib treatment, which may extend the usefulness and applicability of this drug in the clinic." (PMID 26959114, 2016). "Among tumours with data on stage and grade, the majority of BRCA2 mutation carriers presented with stage 2 disease (47 %) and tumours of histologic grade 3 (56.7 %), whereas the majority of BRCA1 mutation carriers presented with stage 3–4 disease (42.9 %) and histologic grade 3 tumours (69.2 %)." (PMID 26857456, 2016). "Taking into account the implications for both the individuals and their family members, we recommend that patients with these neoplasias may be offered BRCA1/BRCA2 genetic testing and we here show that it is feasible to reliably perform this analysis in FFPE tissue." (PMID 27532258, 2016). "In the recent review the following definition has been proposed: “BRCAness is a phenocopy of BRCA1 or BRCA2 mutation; it describes the situation in which an homologous recombination repair defect exists in a tumour in the absence of a germline BRCA1 or BRCA2 mutation”." (PMID 27626685, 2016). "The most significant (likelihood ratio test p = 0.0003) regression model included only covariates age (p = 0.030), a variable for the presence or absence of a germline BRCA1 or BRCA2 mutation (p = 0.062), and a log transformation of the total number of tumor mutations (p = 0.156)." (PMID 26215675, 2015). "Similarly, loss of function due to germline or somatic deletions in tumour suppressor genes may confer drug sensitivity, such as that of high grade serous ovarian cancer with BRCA1 or BRCA2 mutations, to the PARP inhibitor olaparib." (PMID 26569395, 2015). "It seems likely that the sensitivity of BRCA defective tumour cells to PARP inhibitors is caused by their characteristic defect in repair of DNA double strand breaks (DSBs) by homologous recombination (HR), a process controlled by BRCA1, BRCA2 and the DNA recombinase RAD51." (PMID 25883215, 2015). "Triple-negative tumor status was highly predictive of BRCA1 mutation status for women younger than 50 years (LR = 3.73 (3.43 to 4.05)) and 50 years or older (LR = 4.41 (3.86 to 5.04)), and modestly predictive of positive BRCA2 mutation status in women 50 years or older (LR = 1.79 (1.42 to 2.24))." (PMID 25857409, 2014). "However, much less is known about familial tumours (the remaining 5-7%), although studies have noted that BRCA1 tumours are predominantly basal-like while BRCA2 tumours are more hetergeneous and may be HER2-enriched or luminal-like." (PMID 25521701, 2014). "In contrast, our TNBC group was not selected for familial tumour aggregation or age of onset; these differences in inclusion criteria may explain the different BRCA2 mutation frequencies." (PMID 22666503, 2012). "The apparent differences in SNP associations between BRCA1 and BRCA2 carriers, and non-carriers, may be explicable by differences in the prevalence of tumour subtypes." (PMID 22053997, 2011). "Moreover, as mutations in genes other than BRCA1 and BRCA2 affect HR, it is entirely possible that some of the samples classified as “non-BRCA” could also have a similar HR deficiency to BRCA1/2 mutant tumours." (PMID 21750719, 2011). "However, tumour cells that are deficient in the tumour suppressors BRCA1 and BRCA2 proteins, which are important for efficient repair of DSBs by homologous recombination repair, use alternative DNA repair pathways such as base excision repair to compensate for nonfunctional homologous recombination." (PMID 24281034, 2010).
tumor (continued). "Somatic mutations in BRCA1 and BRCA2 have not been found and the involvement of these genes in sporadic tumour development therefore remains unclear." (PMID 19589159, 2009). "The importance of establishing a simple and effective classification scheme to identify such tumours lies in the potential benefit of targeted therapy (PARP inhibitors, platinum drugs) for a much larger group of patients than the relatively few BRCA1 and BRCA2 germline mutation carriers." (PMID 19589159, 2009). "However, some studies have found BRCA2-associated tumours to be negative for HER2 and to over-express CHEK2 (checkpoint kinase 2) and RAD51 (homolog of Saccharomyces cerevisiae Rad51)." (PMID 18275599, 2008). "As both the BRCA1 and BRCA2 proteins are involved in postreplicative DNA repair, reducing the proliferative activity of the breast luminal epithelial cell population from which most tumours are derived should reduce the number of opportunities for replication errors to occur." (PMID 16538216, 2006). "For all families, where an affected individual has been found not to carry the BRCA1 or BRCA2 mutation, that tumour has not been included in the calculations and, of course, only tumours occurring in blood relatives of mutation-positive family members are counted." (PMID 12698193, 2003). "Genomic stability markers, such as BRCA1 and BRCA2, alongside luminal regulators like GATA3, decline progressively with both advancing age and tumor aggressiveness, reaching their lowest levels in TNBC." (PMID 41889413, 2026). "For the BR-05-0566 BRCA2 mutant PDX study, ∼30 mm3 tumor fragment was implanted subcutaneously into female BALB/c mice weeks old." (PMID 41124685, 2025). "For instance, for CRUK0048, a LUAD tumour with 11 clones, ALPACA inferred LOH affecting 13q12.12–13q14.3 (encompassing BRCA2, PDS5B and RB1) to occur in primary tumour clone 2, before seeding a recurrence metastasis lesion." (PMID 40804524, 2025). "Compared to women with BRCA1 and BRCA2 PVs, our data indicate that women with PJS have more favorable tumor characteristics." (PMID 40317347, 2025). "Evaluating the differences in gene expression in various tumor types is critical to elucidate further the functional implications of BRCA1 and BRCA2 in canine tumors." (PMID 40004231, 2025). "In this study, we performed ddPCR to quantify the CNVs of BRCA1 and BRCA2 in the same exons as detected by MLPA, aiming to clarify the limitations in detecting DNA tumor heterogeneity, particularly in cases with ambiguous results." (PMID 40725150, 2025). "For the BR-05-0568 BRCA2 mutant PDX study,∼30 mm3 tumor fragment was implanted subcutaneouslyinto female BALB/c mice weeks old." (PMID 41124685, 2025). "While BRCA2-proficient tumors were resistant to anti-PD1 therapy, the knockout of BRCA2 abrogated tumor growth after immunotherapy treatment." (PMID 40426860, 2025). "Tumor and treatment characteristics in BRCA1 and BRCA2 carriers according to hormone receptor status are reported in the Data Supplement, and those according to the type of first DFS events are reported in the Data Supplement." (PMID 39993249, 2025). "The tumor suppressor PALB2 functions with the BRCA1 and BRCA2 proteins to maintain genomic integrity by homologous recombination." (PMID 39745016, 2025). "The findings largely validated previous reports highlighting the importance of tumor suppressor genes such as ATM, BRCA1, BRCA2, and PALB2 for a limited number of tumor types." (PMID 40072281, 2025).
tumor (continued). "AH cfDNA analysis further revealed multiple SCNAs restricted to the tumor, including duplications in MDM4, ALK, CCND3, and BRAF, as well as deletions in TFRC, FGF3, FGF9, and BRCA2." (PMID 41465072, 2025). "Therefore, tumor-based gene panel testing (FoundationOne®, Foundation Medicine Inc., Cambridge, MA, USA) was performed to evaluate the suitability of PARP inhibitors, which identified a pathogenic BRCA2 mutation (R2318*) with a variant allele frequency (VAF) of 71.52%." (PMID 40065879, 2025). "Men harboring BRCA2 or MMR mutations may benefit from earlier prostate-specific antigen (PSA) testing or colonoscopic screening, whereas azoospermic men with Y-chromosome deletions could undergo periodic testicular ultrasonography and serum tumor-marker assessment." (PMID 41296434, 2025). "Thus, the identification of the BRCA2 variant sheds light on the poorly understood interplay between DNA repair deficiencies and ECM remodeling in OC, providing new insights into their dual role in shaping tumor evolution and suggesting potential targets for novel therapeutic strategies." (PMID 40076915, 2025). "Additionally, while candidate PPV/POVs in known GT genes, including BRCA2 (p.Trp31Arg) and FANCA (p.Arg504Gly) showed tumour associated DDR-like mutational signature enrichment, the 28 PPV/POVs in unknown GT-candidates showing DDR-like mutational enrichment provides further merit for consideration." (PMID 41038821, 2025). "BRCA1 or BRCA2 PVs have been reported in 15−22% of HGSOC, and more than 70% of these tumours are grade 3 carcinomas." (PMID 38443545, 2024). "Over the last decade, researchers have thoroughly investigated the tumor suppressor genes BRCA1 and BRCA2." (PMID 38903278, 2024). "The frequency distribution of PLP variants in the gene structures, including UTR, intron, and exon, was similar among healthy individuals and tumor patients for both BRCA1 and BRCA2." (PMID 38566028, 2024). "PALB2 showed outlier high expression (99th percentile) as did other genes involved in HR including BRCA1 (94th percentile), BRCA2 (100th percentile), and HERC2 (100th percentile) in this tumor." (PMID 38755180, 2024). "Among the upregulated genes were BRCA2 and BLM, also with demonstrated roles in suppression of tumor progression." (PMID 39138582, 2024). "BRCA1 and BRCA2-defective tumors are intrinsically sensitive to PARP inhibitors, both in tumor models in vivo and in the clinic, contrasting to normal cells with an intact HR." (PMID 39684238, 2024). "We report two cases of mutations with low evidence for actionability based on the OncoKB database (BRCA2 S497L and ERBB3 G284R), but for which our local molecular tumor board suggested therapeutic options that led to sustained tumor responses." (PMID 38664720, 2024). "BRCA1, BRCA2, and RAD51 are all key participants in DNA damage repair and show a promoting role in tumor metastasis." (PMID 38983866, 2024). "The tumor suppressor genes BRCA1 and BRCA2 play an essential role in the repair of DSB in the HRR pathway, and mutations in either of these genes are known to increase susceptibility to heritable breast, ovarian, pancreatic, and prostate cancers." (PMID 38807759, 2024). "Due to its importance in DNA damage repair and transcription, and its general importance as a tumor suppressor gene, we sought to validate the interaction between USP44 and BRCA2." (PMID 39767807, 2024). "Considering a distinction for neoplasm, among the 100 MBC patients, 16 were carriers of germline PVs in BRCA2 and only one in BRCA1, whereas 80 were BRCA1/2-wild-type." (PMID 38974244, 2024). "However, the presence of BRCA2 raises the possibility of a secondary role, either as a non-driver mutation or a modifier effect that could impact tumor behavior." (PMID 39935847, 2024).
tumor (continued). "Three germline BRCA1/2 large genomic rearrangements were detected in germline and tumour DNA using Myriad’s myChoice® CDx, including BRCA1 Exon 9-12 deletion (GIS 56), BRCA1 Exon 17 deletion (GIS 70) and BRCA2 Exon 14-16 deletion (GIS 36)." (PMID 36765687, 2023). "Here we have described the structural basis for binding of the BRCA2 C-terminus to the RAD51 nucleoprotein filament, a critical interaction for maintenance of genomic integrity by the BRCA2 tumour suppressor protein." (PMID 37919288, 2023). "Considering both the tumor and the adjacent tissue samples, the ratio between circRNAs and mRNAs was 1.36 and 0.23 circular junctions per 100 linear junctions for BRCA1 and BRCA2, respectively." (PMID 37046838, 2023). "To further examine the finding that patients with somatic BRCA2 PVs were older than those with somatic BRCA1 PVs, we analysed tumour sequencing data from an independent patient cohort from the INOVATe study." (PMID 36805919, 2023). "At the next stage of the work, in the formed sample of patients, using the Accel-Amplicon BRCA1, BRCA2, and PALB2 panel, tumor samples were screened before and after chemotherapy for the presence of mutations in the studied genes." (PMID 37628606, 2023). "En relación a la edad de diagnóstico del tumor, se ha observado que la mediana en portadores BRCA1/BRCA2 afectados de cáncer de mama fue superior a los 40 años." (PMID 38075173, 2023). "The RASSF1A tumor suppressor is closely related to NORE1A and has been shown to regulate BRCA2 activity via the HIPPO pathway." (PMID 37627161, 2023). "The tumor volume, weight and tumor inhibition rate in BRCA1 + NP and BRCA2 + NP treatment groups were significantly lowered, indicating role of wild type BRCA1 and BRCA2 in the tumor microenvironment." (PMID 36631481, 2023). "A marginal residual hazard to opposite direction was seen also for PgR status, tumor size, and the number of affected lymph nodes, suggesting an overall poor fit of the PREDICT ER-positive score for the BRCA2 carriers from CIMBA." (PMID 37173335, 2023). "Significant SNV alterations were observed in BRCA2, ACACB, BRCA1, MSH6 and IFI16 in most tumour types." (PMID 37660060, 2023). "An interesting finding of our study is the trend of BRCA2 and XPD expression in the NAT of HNSCC patients, which was found to be the reverse of those in the tumour biopsies and blood of the same patients." (PMID 37113717, 2023). "Hence, if the functional importance of BRCA1_circRNA_3-2 could be speculated because BRCA1 exon 2 contains the wild-type translation initiation sequence, a putative functional mechanism for BRCA2 circRNA_26-13, which nearly disappears from tumor samples, remains unknown." (PMID 37046838, 2023). "The c.2240A > G, p.(Glu747Gly) VUS in BRCA2 is located outside the known functional domains and has been reported not to affect protein function, in line with the observed HRP phenotype of the tumor." (PMID 37725154, 2023). "Endometrioid tumours of well-differentiated grade provided evidence against VUS pathogenicity for BRCA1 (LR: 0.12 (95% CI: 0.04–0.31), moderate evidence) and BRCA2 (LR: 0.31 (95% CI: 0.12–0.84), supporting evidence)." (PMID 37076566, 2023). "Expression of BRCA2, XPD and APE1 genes in the matched tumour, normal adjacent tissue (NAT) and blood of 12 HNSCC patients and blood of 8 age- and gender-matched controls was determined by quantitative real-time PCR." (PMID 37113717, 2023). "Significant differences in tumor morphology, peripheral features, posterior echoes, echogenic foci, and vascularity were observed between BRCA1 and BRCA2 tumors." (PMID 36905492, 2023).
tumor (continued). "Our functional HR test, performed on the primary tumor samples, already categorized these patients as fHRP, possibly due to the presence of HRP (BRCA2-revertant) subclones." (PMID 36805632, 2023). "Notably, this form of HUWE1-mediated resistance appeared to be particular to tumour cells with BRCA1 exon 11 truncating mutations that are able to express the BRCA1-∆11q protein and was not seen, for example, in tumour cells with BRCA1 exon 22 mutations or in BRCA2 mutant cells." (PMID 37491606, 2023). "Following the approval of therapies targeting homologous recombination defects (HRD) in several cancer settings, tumour testing for the Hereditary Breast and Ovarian Cancer Syndrome (HBOC) genes BRCA1 and BRCA2 has rapidly spread." (PMID 37179432, 2023). "Key to their tumour suppressor activity, BRCA1 and BRCA2 are involved in homologous recombination, a high-fidelity repair pathway for DNA double-strand breaks." (PMID 35668475, 2022). "The tumor suppressor BRCA1 interacts with PALB2 and BRCA2, and localizes to repair foci at DNA lesions similarly to MR64–66." (PMID 35501303, 2022). "The genes BRCA2 (P=0.009),ATM (P=0.004), FANCA (P=0.001), andPARP1 (P=0.011) showed a lower expression in post-NACTresidual tumor samples (n=32) than in pre-NACT biopsy samples (n=98)." (PMID 35293552, 2022). "When comparing expression levels of tumor and normal samples, expression of PRKDC, BRCA2, and ATM genes was higher in the tumors." (PMID 35054819, 2022). "This is especially imperative in determining one‐copy vs. total deletion or LOH of actionable tumor suppressors such as BRCA1, BRCA2, PALB2, and others for which biallelic inactivation would make them eligible for targeted therapy." (PMID 34866317, 2022). "The PALB2 gene product is a tumor suppressor and interacts with BRCA1 and BRCA2 to form a BRCA complex during double-strand break repair." (PMID 36359225, 2022). "i)We do not treat patients depend on the phenotype of the tumor varies whether it is a BRCA1 (mainly TNBC) or a BRCA2 (mainly HR positive) mutations; ii) Adjuvant therapy is a standard systemic treatment and depends on tumor stage, grade, and molecular subtypes, but not gene mutation variants." (PMID 35494038, 2022). "Clearly, iNOS-mediated NO affects the tumor suppressor activities of both BRCA1 and BRCA2 as well as potentiating the expression of HER2." (PMID 35740092, 2022). "In vivo anti‐tumour efficacy of pyridostatin, NU‐7441, paclitaxel and their combination on HCT116 BRCA2−/− xenografts." (PMID 35107878, 2022). "For each tumor, we performed three different assays for BRCA1, and another three distinct assays for BRCA2." (PMID 35203410, 2022). "This is critical in determining one‐copy vs. total deletion or LOH in actionable tumor suppressor such as BRCA1, BRCA2, and PALB2, which are targetable only when inactivated biallelically." (PMID 34866317, 2022). "Those events overlap with many characteristic breast tumor suppressor genes such as BRCA1, BRCA2, CHEK2 with inferred CN lower than basal ploidy." (PMID 35681161, 2022). "We tested 24 tumor samples for BRCA1 and BRCA2 mRNA levels, normalized to the reference genes GUSB, POLR1E, and NUBP1." (PMID 35203410, 2022). "Nucleic acid tumor markers include BRCA1, BRCA2, microRNA, circulating tumor DNA (ctDNA), circulating cell-free DNA (ccfDNA), circulating RNA (circRNA), long noncoding RNAs(lncRNA), etc.." (PMID 35330093, 2022). "The fact that both mammary and overall tumor development were most efficient in P2p53 mice also implies that PALB2 is at least as critical a tumor suppressor as BRCA1 and BRCA2." (PMID 33893322, 2021).